PARP1 (poly(ADP-ribose) polymerase 1)
Diseases named in the same sentence as PARP1 in open-access papers (continued):
Sharing a sentence is not in itself a finding about the gene and the disease.
prostate carcinoma (continued). "It is reported that PARP1 is involved in DNA repair, and Bax/Bcl-2 is a pair of key genes for promoting/inhibiting apoptosis, while RB and PTEN mainly regulate one of the signals of the prostate cancer cell cycle, DNA damage response, and tumor suppression." (PMID 40649870, 2025). "In prostate cancer, NFs take up lactic acid secreted by prostate cancer, deactivate ADP-ribose polymerase 1 (PARP-1), leading to the downregulation of p62 in stromal cells, and activate CAFs by upregulating the expression of CAF markers SDF1, HA, and a-SMA at the transcriptional and protein levels." (PMID 40565047, 2025). "In addition, they performed mediation analysis and confirmed that some proteins, PARP1, GDI2, and TMEM106A, exerted indirect effects on some diseases, such as prostate cancer, uterine leiomyoma, and idiopathic pulmonary fibrosis through telomere length." (PMID 38431573, 2024). "Our data suggests the presence of a double-negative feedback loop between MALAT1 and PARP1 in both AR-negative and AR-positive prostate cancer cell lines." (PMID 37812088, 2023). "The objective of the current pilot study was to evaluate the dynamic range of PARP1 expression in prostate cancer patients with and without HRR genomic alternations utilizing FTT-PET." (PMID 35701722, 2022). "The activity of PARP1 is believed to be a new biomarker for sensitivity to PARP inhibitor, as it has been reported that increased PARP1 activity correlates positively with disease progression in prostate cancer." (PMID 36010882, 2022). "Preliminary reports utilizing several Auger-emitting theranostic tracers, such as 123I-MAPi (Iodine-123 Meitner-Auger PARP1 inhibitor) and the already cited 125I-KX1 provided encouraging results in tumors other than prostate cancer, such as glioblastoma multiforme and neuroblastoma." (PMID 33809749, 2021). "Poly [ADP-ribose] polymerase 1 (PARP-1) inhibitors, which are already used in breast, ovarian, and prostate cancer, could establish a novel therapeutic pathway." (PMID 33461603, 2021). "Therefore, piperine via PARP-1 cleavage, inhibition of NF-κB, downregulation of STAT-3, and activation of caspase-3 can inhibit prostate cancer and cell proliferation." (PMID 35069196, 2021). "While a number of clinical trials are ongoing to evaluate PARP1 inhibition as a prostate cancer therapy, PARG inhibition as a therapeutic strategy has not yet been tested." (PMID 32123273, 2020). "Thus, the study of genetic models of prostate cancer showed an essential role for PARP-1 in sustaining AR transcriptional function; furthermore, PARP-1 activity increases during disease progression." (PMID 31366128, 2019). "In considering the multifaceted role of PARP-1, it is worth mentioning that many reports showed increased levels of PARP-1 or, more generally, pointed to PARP-1 involvement in carcinogenesis, as for instance is the case for primary prostatic cancer." (PMID 31877876, 2019). "In prostate cancer, autoantibody frequency to PARP1/BRCA1/BRCA2 were 2.8% (3/107), 28.0% (30/107) and 4.7% (5/107), 1.9% (2/107), 0.9% (1/107) and 1.9% (2/107) were shown to have autoantibody to PARP1 and BRCA1, PARP1 and BRCA2, or BRCA1 and BRCA2." (PMID 25865228, 2015). "While therapeutic targeting of transcription factor oncogenes is intrinsically challenging, on the basis of the interaction of ERG with the DNA repair enzyme PARP1 and DNA protein kinase DNA-PKc, use of PARP inhibitors was shown to inhibit growth of TMPRSS2-ERG-positive prostate cancer xenografts." (PMID 26684754, 2015). "This idea is in line with previous evidence demonstrating how PARP1 inhibitors blocked ETS-positive but not ETS-negative prostate cancer xenograft growth." (PMID 25906745, 2015). "PARP-1 expression and activity are also required for cancer cell invasion mediated by ETS transcription factors – whose fusion products drive Ewing’s sarcoma, acute myeloid leukemia, and prostate cancer – and the Ewing’s sarcoma fusion protein EWS-FLI." (PMID 24350055, 2013).
prostate carcinoma (continued). "In addition, GST pull-down assays of DU145 prostate cancer cells using individual GST-fused domains of BIN1 and PARP1 showed BIN1 bound to the automodification domain of PARP1 through the BIN-amphiphysin-Rvs-related (BAR-C) domain of BIN1." (PMID 22778941, 2012). "However, to date, no study has investigated the efficacy of a PARP-1 targeting Auger emitter in prostate cancer." (PMID 36834491, 2023). "Interaction of CEBPA and PARP1 has been previously demonstrated in prostate cancer, however, we could not validate their interaction in AML cells due to overlap with unspecific antibody/bead complex signals." (PMID 33911178, 2021). "Non-NAD+-like PARP1 inhibitors, binding to sites different from the NAD+ binding site, have been studied for prostate cancer treatment." (PMID 34639169, 2021). "In turn, inhibition of PARP1 reduces ETS-positive, but not ETS-negative, prostate cancer xenograft growth." (PMID 24616882, 2014). "Alternatively, this may simply be confirming highly variable PARP-1 IHC regardless of BRCA status in patients with ovarian, breast, and prostate cancers, as shown by others." (PMID 35701722, 2022). "While PARP1 levels are not regulated by AR, PARG inhibition has a potential to synergize with castration therapy and be more effective in reducing cancer burden in men with advanced prostate cancer." (PMID 32123273, 2020).
melanoma (92 papers, 2007 to 2025). A malignant, usually aggressive tumor composed of atypical, neoplastic melanocytes. "PARP1 has been previously associated with aggressive melanoma, but has shown context-dependent efficacy on melanoma cell death and invasion." (PMID 38183207, 2025). "Davies at al. reported an association between a rare, inherited variant in the PARP1 (polyadenosine diphosphate-ribose polymerase 1) gene and melanoma survival." (PMID 40869905, 2025). "In melanoma patients, high PARP-1 expression was associated with worse melanoma-specific survival and overall survival (OS) for mucosal melanomas, and OS in late-stage metastatic melanomas." (PMID 39201718, 2024). "Three genes of the final associative network, CASP8, ATM, and PARP1, are associated in GWAS with melanoma as an example of positive associations of cancer with neurodegenerative disorders characterizing different molecular pathophysiology." (PMID 37298337, 2023). "To investigate the underlying molecular mechanisms regulating radioresistance in WTBRAF melanoma and identify potential targets, we searched for RTKs that are associated with PARP-1 after RT." (PMID 37215708, 2023). "For example, PARP1 was identified as the target gene regulated by the melanoma-associated locus 1q42.12, agreeing with previous reports of PARP1 acting as a melanoma susceptibility gene in a melanocyte lineage-specific manner." (PMID 36171609, 2022). "PARP-1 promotes melanoma risk by activating oncogene transcription and cell proliferation, independently of PARylation." (PMID 36077221, 2022). "To conclude, in our in vitro model, increased PARP1 expression was associated with enhanced invasiveness of melanoma cell lines." (PMID 33572647, 2021). "Perhaps personalized medicine approach is necessary to pre-select patients with melanomas predisposed to synthetic lethality mediated by PARP1 inhibitor." (PMID 27705909, 2016). "In summary, PARP1 inhibitor seems to offer additional treatment opportunity to pre-selected melanomas displaying LIG4 (and/or XRCC4) deficiency." (PMID 27705909, 2016). "This study showed that the investigated PARP1 SNP was associated with increased survival of melanoma patients and that the reduced expression of PARP1, affecting both melanoma growth and angiogenesis, may positively impact on melanoma progression." (PMID 40869905, 2025). "To this end, we used the Duolink PLA assay to monitor such interaction and indeed we observed a significant increase in PLA signals with RT compared to non-irradiated cells in the same conditions as above indicating c-Met/PARP-1 association after RT in melanoma." (PMID 37215708, 2023). "According to the authors, the risk allele then translates into higher PARP1 levels, which may promote melanoma formation by rescuing cells from BRAFV600E oncogene-induced senescence." (PMID 33383480, 2021). "PARP1 levels are elevated in a variety of tumor cells, including breast, lung, ovarian, prostate, and melanomas." (PMID 39893479, 2025). "Elevated levels of PARP-1 were observed in many types of tumor cells, such as breast, lung, ovarian, prostate, and melanomas." (PMID 39893479, 2025). "Piceatannol, a structural analog of resveratrol found in grapes and berries, is known to induce caspase-dependent apoptosis, nucleosomal DNA fragmentation, and PARP1 cleavage in many human cancer cell lines, including leukemia, melanoma, and lymphoma." (PMID 38794181, 2024). "PARPi and PARP-1 knockdown led to the downregulation of Snail1 and increases in E-cadherin in melanoma cells." (PMID 39201718, 2024). "Among the genes we identified, many are known melanoma susceptibility genes including CASP8, ARNT, and OCA2 (downregulated), PARP1, SETDB1, MTAP, SLC45A2, and MC1R (upregulated), and MX2 (both up‐ and downregulated)." (PMID 38308491, 2024). "Herein, we identify PARP1 among the mRNA Binding Proteins that specifically target the X1 3'UTR in melanoma cells." (PMID 37013641, 2023).
melanoma (continued). "After treatment, excessive DNA damage in melanoma cells leads to an increase in the expression of pro‐apoptotic genes (Caspase‐3) and a decrease in the expression of DNA repair gene (PARP1) and anti‐apoptotic gene (Bcl‐2) to activate the apoptosis pathway." (PMID 36241419, 2023). "In summary, our study unveils PARP1 as a negative regulator of the highly oncogenic MAPK pathway in melanoma, through the modulation of BRAF-X1 expression." (PMID 37013641, 2023). "Secondly, and to evaluate the possible role of PARP-1 in melanoma radioresistance, we investigated the benefit of inhibiting PARP-1 in three melanoma cells (2 radioresistant: HBL and MM162, and one radiosensitive: LND1)." (PMID 37215708, 2023). "As targeting c-Met or PARP-1 affects melanoma cell survival and response to RT, we examined a possible RT-promoted interaction between c-Met and PARP-1." (PMID 37215708, 2023). "Second, to provide more evidence about the activation of PARP-1 by c-Met under RT in melanoma, we evaluated the radiosensitizing effect of the dual combination of Crizotinib and Olaparib." (PMID 37215708, 2023). "Previous studies reported that in melanoma, PARP1 interacts with the C-terminal domain of HIF-1a and regulates the expression of HIF-1a." (PMID 37821935, 2023). "Third, as melanoma radioresistance can mainly be due to its DNA repair efficiency, we investigated the benefit of inhibiting PARP-1 to oppose such resistance in WTBRAF melanoma." (PMID 37215708, 2023). "First, we checked and found a relatively high constitutive expression and activity of PARP-1 in all melanoma lines." (PMID 37215708, 2023). "DNA damage repair genes PARP1 was downregulated substantially in Paclitaxel‐treated and ‐irradiated melanoma cells." (PMID 36241419, 2023). "A study uncovered that PARP-1 can activate the snail signaling pathway to induce EMT in melanoma cells." (PMID 37535572, 2023). "Immunoblots showed a concentration-dependent increase of the cleaved PARP1 band and a concomitant decrease of its full-length band, in all BRAF-mutated melanoma cell lines." (PMID 36674794, 2023). "Through activating PARP1 and the downstream NF-κB signaling, anti-melanoma DNA-damaging drugs induce melanoma cell SASP." (PMID 35801078, 2022). "The involvement of PARP1 is important in melanoma tumorigenesis; in normal melanocytes, PARP1 is inactive and inhibits CXCL1 expression, while in melanomas PARP1 is active." (PMID 35054978, 2022). "The synthetic peptide Rb4 significantly reduced B16F10-Nex2 melanoma growth by triggering PARP-1-mediated tumor-cell necrosis." (PMID 35190586, 2022). "A subset of MM is characterized by the overexpression of CHAF1B and poly (ADP-ribose) polymerase 1 (PARP-1), another regulator of DNA repair that is associated with aggressive melanoma behaviour." (PMID 34073937, 2021). "Axitinib did not induce apoptosis in endothelial cells in vitro and in fibrosarcoma and melanoma bearing mice, whereas sorafenib forced the expression of cleaved PARP-1 and caspase-3 in HUVECs and elevated the proportion of cells in the sub-G1 fraction." (PMID 34829859, 2021). "So far, in vitro and clinical studies are in line with our observations and seem to indicate a significant role of PARP1 in melanoma progression and the development of metastases." (PMID 33572647, 2021). "Our current results indicate that the invasiveness of the examined melanoma cells correlated positively with the level of PARP1 in these cells." (PMID 33572647, 2021). "One previous study demonstrated that SNA coupled with the p65 subunit of NF-κB and PARP1 bound to the FN1 promoter at proximal (−236/+72) region to activate FN1 transcription in melanoma cells." (PMID 34571852, 2021). "In another study, application of veliparib (ABT-888, PARP1 inhibitor) resulted in an increased apoptosis level, decreased migration, and invasiveness of the A375 melanoma cell line." (PMID 33572647, 2021).
melanoma (continued). "The aim of the study was to explore the possible involvement of PARP1 in melanoma development and progression." (PMID 33572647, 2021). "Up-regulation of PARP1 in melanoma cells in the whole cohort of patients had strict correlations with unfavorable histopathologic parameters such as greater Breslow thickness, presence of ulceration, and high mitotic activity." (PMID 33572647, 2021). "Our in vitro studies showed that melanoma cells exhibited significantly higher PARP1 expression compared with normal melanocytes." (PMID 33572647, 2021). "In primary mucosal melanoma, it has been observed that a higher PARP-1 expression was significantly associated with higher mitotic activity, which showed that PARP-1 is involved in the regulation of mitosis." (PMID 34830749, 2021). "In melanoma, senescent cells produce a secretome that displays pro-invasive and pro-tumorigenic properties and that depends on PARP-1 and NF-κB." (PMID 33371508, 2020). "XPA promotes autophagy in resistant melanoma cells after cisplatin treatment through facilitating PARP1 activation." (PMID 32635505, 2020). "Correlations between PARP1 overexpression in melanoma cells and presence of tumoral PD-L1 and IDO1 were observed (p = 0.04, and p = 0.0001, respectively)." (PMID 32380691, 2020). "By Fisher’s exact test, up-regulation of PARP1 in mucosal melanoma cells was significantly correlated with highly mitogenic tumors (p = 0.02)." (PMID 32380691, 2020). "In our study, we observed a significant correlation between high nuclear expression of PARP1 and enhanced immunoreactivity of PD-L1 in mucosal melanoma cells." (PMID 32380691, 2020). "In melanoma, PARP1 is mainly known to regulate NFκB activity, thus affecting CXCL1 cytokine transcription." (PMID 32455851, 2020). "In the current study, we investigate the prognostic role of PARP1, PD-L1, and IDO1 protein expression and explore the possible associations between tumoral PARP1, PD-L1, and IDO1 expression in a series of mucosal melanomas." (PMID 32380691, 2020). "Regarding apoptotic escaping and cell survival, melanoma cells collected from acidic, transient and chronic, clones show a clear reduction of cleaved PARP1 and an enhanced expression of EGFR." (PMID 31275384, 2019). "When we tested the cleaved poly ADP-ribose polymerase 1 (PARP1), as a marker of apoptosis, chronic acidic melanoma cells recovered from agarose-coated dishes show a more apoptosis resistance phenotype than transient acidic cells and control cells." (PMID 31275384, 2019). "Our findings provide a strong rationale for the development of 2HF as a topical therapy and lay the groundwork for the combination with sunitinib or PARP1 inhibitors in the treatment of melanoma." (PMID 31615091, 2019). "A recently published study showed potentiation of the cytotoxic effect of alkylating agents on melanoma cells by addition of a PARP1 inhibitor." (PMID 31615091, 2019). "Because of their observed efficacy in BRCA-mutated tumors and the role of PARP-1 in cellular repair mechanisms, PARP inhibitors were introduced into melanoma therapy." (PMID 31133874, 2019). "PARP-1 inhibition has recently been employed in both mono- and combination therapies in various malignancies including melanoma with both promising and contradicting results reported." (PMID 31133874, 2019). "We noted that other genes involved in sensing DNA damage and repairing double stranded breaks (e.g. PARP1, ATM, APEX1) are in linkage disequilibrium with SNPs associated with melanoma risk in GWAS." (PMID 30681412, 2019). "Both HS294T and SKMEL-2 melanoma cells underwent apoptosis after 72 hours of treatment with 5-Aza-2'-Deoxycytidine (DAC) as indicated by cleavage of PARP1 and lamin A/C." (PMID 30485296, 2018). "The expression of cleaved forms of caspase-3 and poly(ADP-ribose) polymerase-1 (PARP-1) suggested that the extract induced apoptosis through caspase-3 activation in both human malignant melanoma (SK-Mel-28) and human cervical cancer (HeLa) cell lines." (PMID 28208804, 2017).